CRKL (CRK like proto-oncogene, adaptor protein)
Diseases named in the same sentence as CRKL in open-access papers (continued):
Sharing a sentence is not in itself a finding about the gene and the disease.
tumor (continued). "With the use of IHC staining we have established the localization of CRKL protein in the squamous epithelium of the non-cancer larynx and tumor samples." (PMID 31913340, 2020). "To further investigate CRKL and its potential oncogenic activity in LSCC we performed functional analyses aimed at determining the effect of siRNA knockdown on proliferation and migration of the tumor cells." (PMID 31913340, 2020). "Our results showed that miR-429 and CRKL affected the expression level of Raf/MEK/ERK pathway- and EMT-related molecules, we speculated miR-429-CRKL axis might mediate tumor migration and invasion via regulating Raf/MEK/ERK-EMT pathway." (PMID 29403024, 2018). "In line with this, we found that although CrkL-deficient T cells could clear hematopoietic tumors, they failed to clear the same tumor growing subcutaneously, highlighting the role of CrkL in controlling T cell migration into peripheral tissues." (PMID 32391120, 2020). "Therefore, SLC7A5 could be one of the downstream genes of CRKL in SGC-7901 cells, which leads the tumor cells to proliferate, invade and migrate." (PMID 27846244, 2016). "However, CrkL KO T cells could not clear the same tumor when it was growing subcutaneously, highlighting the role of CrkL in controlling T cell migration into peripheral tissues." (PMID 32391120, 2020). "Moreover, ETV6 upregulation was positively correlated with CRKL upregulation, and two negative correlations were also established for ETV6 and CRKL upregulation with miR-429 downregulation in both hepatocarcinoma patients’ tumorous tissues and hepatocarcinoma cells." (PMID 32326970, 2020). "Importantly, CRKL levels in pan-cancer TCGA analyses were predictive of survival and CRKL knockdown suppressed experimental metastases in vivo without affecting primary tumor growth." (PMID 26728244, 2016). "While VASP and RAPH1 expression did not significantly differ between non-tumor and tumor tissue, CRK and CRKL exhibited an opposite expression pattern." (PMID 39126118, 2024).
cancer (54 papers, 2012 to 2026). A tumor composed of atypical neoplastic, often pleomorphic cells that invade other tissues. "A growing body of evidence suggests that the dysregulation of Crk and CrkL is linked to various human diseases, such as cancer and pathogen infections." (PMID 40362257, 2025). "The cytoplasmic adapter protein, CrkL, is integrated into tyrosine kinase signal cascade pathways in humans in response to diverse stimuli that can lead to cancer susceptibility." (PMID 35203305, 2022). "It will be necessary to examine both copy number alterations and protein level changes in cancer tissue and study underlying mechanisms on how Crk and CrkL transcripts and proteins are upregulated in cancer." (PMID 33801580, 2021). "Knockdown CRKL expression in PTEN‐deficient cancer cells resulted in an enhances in p110b‐dependent PI3K signaling and cancer cell growth." (PMID 34114685, 2021). "Recent studies have demonstrated that CrkL acts a pivotal part in cell proliferation and associated with the migration and invasion in range of cancers such as bladder, breast cancers, lung, stomach, and liver." (PMID 34114685, 2021). "Rap1 (in KEGG) and ras (in KEGG) signaling are activated by lung cancer oncogene CRKL whose focal amplification (secondary mutation) was reported to be associated with acquired resistance to EGFR inhibitor." (PMID 28288164, 2017). "CRKL deregulation is linked to the development and progression of a variety of cancers." (PMID 38683131, 2024). "The deregulation of CRKL associated with the development and progression of cancers." (PMID 33523562, 2021). "CRKL deregulation has been linked to the development and progression of a variety of cancers." (PMID 32326970, 2020). "Establishing the contribution of the p130Cas-Crk/CrkL axis to cancer will facilitate the development of cancer drugs targeting the axis to inhibit cancer cell dissemination and improve patient outcomes." (PMID 40362257, 2025). "Inhibitors that specifically block the interaction between p130Cas and Crk/CrkL without affecting the protein levels will enable to establish the contribution of the p130Cas-Crk/CrkL axis to cancer." (PMID 40362257, 2025). "This review underscores the critical role of the p130Cas-Crk/CrkL axis in orchestrating cell transformation, migration, and invasion, the hallmarks of cancer." (PMID 40362257, 2025). "Further detection of CRKL expression in TNBC showed that CRKL was highly expressed in cancer tissue." (PMID 38717531, 2024). "miR‐429‐CT10 regulation of kinase‐like (CRKL) axis involved in development, progression and metastasis of cancers." (PMID 38683131, 2024). "CRKL was also reported to enhance the glucose metabolism of cancer cells by activating PI3K/Akt, thus promoting the occurrence of hepatocarcinoma." (PMID 38289488, 2024). "CRKII and CRKL deregulation have been proved to be involved in the development and progression of a variety of cancers." (PMID 38683131, 2024). "Although several studies determined the direct or indirect network between PIK3CA, KDR, GAB1, VEGFA, PLCG, and CRKL and hsa-miR-429 in various cancers, the functional regulation of these genes in Bag-1 deficiency conditions is still needed to elucidate." (PMID 37533517, 2022). "In HCC, miR-429 can target CRKL to inhibit cancer cell migration and invasion by inhibiting Raf/MEK/ERK pathway." (PMID 35468721, 2022). "Cancer cell migration and invasion were also inhibited by Crk or CrkL knockdown and promoted by Crk or CrkL overexpression." (PMID 33801580, 2021). "Clinical observations suggest increased CrkL expression is directly correlated with aggressive and invasive cancer phenotypes in ovarian and lung cancer." (PMID 34417497, 2021). "The effect of Crk and CrkL on the cell cytoskeleton has also been demonstrated in cancer cell lines." (PMID 33801580, 2021).
cancer (continued). "Considering that either Crk or CrkL has been studied in many cancer types, it is likely that cancers in different tissue types have different preferential dependences on Crk and CrkL." (PMID 33801580, 2021). "Herein, our work highlights the clue to suppress CRKL in inhibiting glucose metabolism of hepatocarcinoma cells, which provides a new fundamental sight of molecule‐targeted therapy of cancer." (PMID 33523562, 2021). "Taken together, these studies demonstrate that Crk and CrkL play critical overlapping roles in the reorganization of the cytoskeletal network and are required for the spreading of fibroblasts and cancer cells." (PMID 33801580, 2021). "Cancer cells are probably more prone to a reduction in protein levels or activities of Crk and CrkL." (PMID 33801580, 2021). "Expression of Crk or CrkL is elevated in multiple human cancers, and the overexpression is positively correlated with poor prognosis." (PMID 33801580, 2021). "CRKL up‐regulation potentially promotes hepatocarcinogenesis via enhancing cancer cells’ glucose metabolism through increasing GLUT1 expression, potentiating HKII activity and inactivating GSK3β activity." (PMID 33523562, 2021). "Effects on cancer cell migration and invasion are the most extensively studied function of Crk and CrkL." (PMID 33801580, 2021). "Taken together, these studies demonstrate essential functions of Crk or CrkL in cell cycle progression and cell proliferation in a variety of cancer cell lines." (PMID 33801580, 2021). "The results appear to be in a clear contrast to the results from the numerous studies of Crk and CrkL overexpression in cancer tissues." (PMID 33801580, 2021). "Contribution of Crk and CrkL to anchorage-independent growth was demonstrated in several cancer cell lines." (PMID 33801580, 2021). "A clear understanding of the individual and combined functions of Crk and CrkL in each cancer type is critical to identifying the therapeutic target." (PMID 33801580, 2021). "Because Crk knockdown alone did not reveal contributions of Crk to these cellular functions, our study demonstrates the importance of combining single and double knockdown strategies to fully understand the functions of Crk and CrkL in cancer." (PMID 33561443, 2021). "The high expression level of CrkL has been related to advanced‐stage cancers with high‐grade aggressiveness and poor prognosis." (PMID 34114685, 2021). "Immunohistochemical examination of Crk and CrkL expression in tissue specimens from cancer patients revealed that many cancers had elevated protein levels of Crk or CrkL." (PMID 33801580, 2021). "All these studies of Crk and CrkL using cancer tissues and cancer cell lines propose Crk and CrkL as promising therapeutic targets for cancer treatment." (PMID 33801580, 2021). "Studies of the role of Crk and CrkL in cytoskeletal network rearrangement have provided insights into alterations of the cytoskeleton in cancer cells." (PMID 33801580, 2021). "CRKL itself has been reported as a possible candidate for cancer diagnosis and prognosis and as a therapeutic target for certain cancers." (PMID 33094104, 2020). "The protein complexes formed by CRKL and other protein partners are important for biological processes which are recurrently deregulated in cancer progression, like: migration, cell proliferation, survival and adhesion." (PMID 31913340, 2020). "CRKL performs a vital function in the aggressive malignancy of human cancers and is pleiotropic in regulation of proliferation, adhesion, migration, invasion, and phagocytosis of cells." (PMID 33094104, 2020). "Because of its role as a multi-functional adaptor protein in signal transduction, CRKL deregulation is involved in a variety of cancers." (PMID 32326970, 2020). "This is the first report of CRKL-regulation of the alternative splicing of a number of genes critical in tumorigenesis and cancer progression, which is consistent with CRKL reported role as a signaling adaptor and a kinase." (PMID 31133010, 2019).
cancer (continued). "Previous work has shown that CrkL, which is an intracellular protein, can be secreted from cancer cells in vitro and bind to the cell membrane through interaction with β1 integrin." (PMID 31323992, 2019). "CRKL is overexpressed in various types of human cancer and can induce cancer cell proliferation and invasion." (PMID 31133010, 2019). "We then selected 40 cancer samples with 20 showing high CRKL expression and 20 showing low, which were analyzed for the potential impact of CRKL on alternative splicing regulation of cancer transcriptome." (PMID 31133010, 2019). "It has been shown that increased levels of CrkL protein correlate with cancer progression in various cancers." (PMID 31323992, 2019). "To validate the ASEs of cancer related genes regulated by CRKL by a different method, we selected 43 ASEs to perform RT-qPCR experiment." (PMID 31133010, 2019). "CRKL is predominantly detected in the epithelial cells with low expression in normal lung tissues, and its overexpression is correlated with poor cancer prognosis." (PMID 27078848, 2016). "Our findings have identified CRKL as critical to integrin-dependent activation of the cancer cells and localization of activated FAK and Src to focal adhesions." (PMID 26728244, 2016). "Accumulating evidence has been reported and suggested that dysfunction of CRKL as a key factor in variety of human diseases, including inflammation and carcinomas." (PMID 27846244, 2016). "Elevated levels of Crk proteins (CrkI, CrkII, CrkL) are observed in human cancers, including those of epithelial origin, such as breast." (PMID 22569336, 2012). "They revealed that the expression of CRKL mRNA in a cancer cell line was stimulated by proteins released by Helicobacter pylori, although the underlying mechanism was not resolved and the CRKL genomic copy number was not analyzed." (PMID 22591714, 2012). "CRKL (CRK Like Proto-Oncogene) as a number of the Crk family that encodes a protein kinase that contains the SH2 and SH3 (SRC homology) domains, which is expressed in many cancer tissues." (PMID 38717531, 2024). "Therefore, developing various inhibitors, and stimulators as well, that are specific to Crk or CrkL or both will serve as essential tools in therapeutic cancer intervention and basic science research." (PMID 33801580, 2021). "A close comparison of the Crk- and CrkL-mediated effects between normal and cancer cells may provide valuable insights into therapeutics." (PMID 33801580, 2021). "Crk and CrkL are overexpressed in many types of human cancer, correlating with poor prognosis." (PMID 33801580, 2021). "Therefore, it is premature to conclude why some cancer cells depend on Crk and others depend on CrkL to proliferate." (PMID 33801580, 2021). "Several reviews have previously discussed the critical roles of Crk and CrkL in cancer." (PMID 33801580, 2021). "Crk and CrkL are also elevated in other types of cancer and suggested as therapeutic targets." (PMID 33561443, 2021). "If a certain protein-protein interaction is induced only when cells overexpress Crk and CrkL, it may be a cancer-specific event and serve as a good therapeutic target." (PMID 33801580, 2021). "Crk and CrkL have been studied for their roles in normal and cancer cell proliferation." (PMID 33801580, 2021). "Henceforth, multiple studies suggest CrkL is an important factor in the study of cancer." (PMID 34417497, 2021). "Consequently, the existing data for Crk and CrkL provide valuable but limited insights into the contribution of Crk and CrkL to cancer cell function." (PMID 33801580, 2021). "In addition, CRKL, frequently unregulated in several malignant tumors, positively regulates the progression of cancers by promoting cell proliferation and metastasis." (PMID 34434896, 2021). "The miR-124-3p-CRKL axial regulated pathway may offer valuable indications for cancer research, diagnosis, and treatment." (PMID 33094104, 2020).
cancer (continued). "Importantly, in non-cancer laryngeal epithelium we demonstrated that CRKL shows moderate nuclear-cytoplasmic localization only in the proliferating cells." (PMID 31913340, 2020). "The deregulations of CRKL have been correlated with development and progression of various cancers." (PMID 33094104, 2020). "Additionally, CRKL has been proposed as a possible candidate for cancer diagnosis and prognosis and as therapeutic target for certain cancers." (PMID 33094104, 2020). "CrkL can be secreted from cancer cells binding to β1 integrin on the cell membrane." (PMID 31323992, 2019). "In addition, CRKL was demonstrated to be an oncoprotein contributing to malignant cell growth and chemoresistance and promoting cancer cell invasion through a Src-dependent pathway." (PMID 31133010, 2019). "Because cancer tissues are complicated in cell types and deregulated genes, these potential CRKL-regulated ASEs could be complicated by the contribution of other factors." (PMID 31133010, 2019). "CRKL gene amplification and high levels of protein expression were reported in many human cancers, suggesting that CRKL may act as an oncogene." (PMID 28558797, 2017). "CRKL signaling is highly pleiotropic and its role in cancer is still being elucidated." (PMID 25897431, 2015). "CRKL overexpression may be a cancer‐specific event and serves as a good therapeutic target." (PMID 36653904, 2023). "Thus, the scientific literature has created an enigma; it appears that Crk and CrkL are important in several cancers, but it is unclear whether a single one of these genes is the culprit or both in combination." (PMID 33561443, 2021). "In addition, EMT and chemoresistance required Crk or CrkL in several cancer cells." (PMID 33801580, 2021). "Therefore, Crk and CrkL have been proposed as therapeutic targets for cancer treatment." (PMID 33801580, 2021). "Since many human cancer types exhibit elevated expression of Crk and CrkL, the protein levels of Crk and CrkL in cells may be a critical deciding factor between normal and oncogenic functions of Crk and CrkL." (PMID 33801580, 2021). "Thus, CRKL plays oncogenic roles in various types of cancer." (PMID 34076957, 2021). "Therefore, Crk and CrkL have been proposed as potential therapeutic targets in these cancers." (PMID 33561443, 2021). "Although the lack of studies about a potential correlation between transcript and protein levels in various cancer types makes it difficult to draw any conclusion, it is possible that many cancers may modulate Crk and CrkL expression at the level of translation." (PMID 33801580, 2021). "Unlike the systematic and comprehensive approaches made in the field of development, however, many of the early studies of Crk and CrkL in cancer have lacked thorough and quantitative comparisons among phenotypes that resulted from individual and combined gain or loss of Crk and CrkL." (PMID 33801580, 2021). "Therefore, the insufficiency of miR-124-3p inversely correlated with CRKL upregulation might contribute to HCC clinical progression via elevated malignancy of HCC cancer cells through C-JUN, BAX, and BCL-2 deregulations." (PMID 33094104, 2020). "Thus, a PTEN/Src/p130Cas axis activates CRKL/p110β in PTEN-null cancer cells." (PMID 35582276, 2019). "Previous studies have reported that CRKL could affect cancer cell proliferation." (PMID 29403024, 2018). "CRKL belongs to the CRK adapter protein family and participated in the development and progression of many cancers." (PMID 38289488, 2024). "ALK has been described in a range of human cancers involved in cancer initiation and progression via activating multiple signaling pathways, such as the PI3K-AKT, CRKL-C3G, MEKK2/3-MEK5-ERK5, JAK-STAT and MAPK signaling pathways 19-23." (PMID 33391411, 2021).